CYP2E1 (cytochrome P450 family 2 subfamily E member 1)
Diseases named in the same sentence as CYP2E1 in open-access papers (continued):
Sharing a sentence is not in itself a finding about the gene and the disease.
breast carcinoma (continued). "The CYP2E1-mediated ER stress and UPR were assessed in breast cancer cells by monitoring the luciferase activity of the pCAX-HA-2xXBP1deltaDBD9anATG)-Luc-F reporter in breast cancer cell lines transfected with PCDNA3, CYP2E1, scrambled RNAi, or CYP2E1 shRNA." (PMID 24207099, 2013). "Finally, the stage of disease may determine the appropriate treatment as for example the levels of the CYP2E1 biomarker are high in early stages of breast cancer and gradually decline in later stages of tumor development, therefore stratifying patients according to the CYP2E1 cellular levels." (PMID 22911518, 2012). "CYP2E1, CYP2C19, CYP2D6, mEH and NAT2 genotype frequencies in control subjects and in patients with breast carcinoma." (PMID 18423013, 2008). "Cytochrome P450 2E1 (CYP2E1) is the principal P-450 responsible for the metabolism of ethanol and it has been shown to contribute to reactive oxygen species (ROS) generation in breast cancer cells." (PMID 30611309, 2019). "Another study in Taiwan reported that the combination of CYP2E1 and GSTM1 was associated with breast cancer without the habits of cigarette smoking and alcohol consumption." (PMID 17603900, 2007). "Taken together the role of CYP2E1 in inducing ROS generation and the fact that CYP2E1 is differentially expressed in early rather than later stages of breast cancer implies that this cytochrome P450 isoenzyme might regulate migration of breast cancer cells." (PMID 24207099, 2013).
Cirrhosis (21 papers, 2006 to 2025). A chronic disorder of the liver in which liver tissue becomes scarred and is partially replaced by regenerative nodules and fibrotic tissue resulting in loss of liver function. "Moreover, although there is variation in CYP450 activity among both healthy and diseased livers, cirrhosis was associated with a significant decrease in CYP2E1 activity." (PMID 29067481, 2018). "Patients with high levels of RI (RIhigh, RI > 136.17) were more likely to have higher AFP level and cirrhosis stage as well as CYP2E1 activity, indicating that the established method has substantial clinical value." (PMID 35314790, 2022). "For CYP2E1, we identified healthy individuals with one, two, or three copies, whereas all patients with cirrhosis carried two copies of the gene." (PMID 34068303, 2021). "CYP2E1 was noticeably different asit showed a lower relative abundance in severe cirrhosis comparedto other groups." (PMID 34428046, 2021). "Going from the control group to severe cirrhosis,CYP2E1 dropped down from the third most abundant CYP to the fifthrank." (PMID 34428046, 2021). "Activity of CYP2E1 was only lost in patients with decompensated cirrhosis, and also CYP2D6 function was relatively preserved." (PMID 27754327, 2016). "In addition, because the induction of hepatic activity of ADH is also inhibited after chronic consumption of alcohol, the generation of ROS through the metabolism of CYP2E1 can mediate liver damage, including fibrosis and cirrhosis, in ALD." (PMID 38542468, 2024). "The RIs correlated well with AFP, cirrhosis stage, and CYP2E1 activity." (PMID 35314790, 2022). "The liver-selective hepatotoxin diethylnitrosamine (DEN) undergoes CYP2E1-mediated oxidation to become a genotoxin, leading to hepatocyte apoptosis and tissue damage that can progress to cirrhosis and HCC." (PMID 33871359, 2021). "However, a previous study found that CYP2E1 activity was lower in patients with moderate or severe cirrhosis." (PMID 27203676, 2016). "However, in adults, therapeutic doses of acetaminophen have been associated with liver injury in patients who take acetaminophen chronically, are malnourished, chronically abuse alcohol, or have cirrhosis due to glutathione depletion or alcohol induction of CYP2E1." (PMID 40827188, 2025). "However, the increased levels of pre-carcinogen activation might explain in part why CYP2E1 activities were higher in HCC patients than in simple cirrhosis patients." (PMID 27203676, 2016). "Therefore, additional studies are needed to confirm whether changes in CYP2E1 activity are critical factors in the progression of cirrhosis to HCC." (PMID 27203676, 2016). "Compared with controls, the Km values of CYP1A2, CYP2A6, CYP2B6, CYP2C8, CYP2C19, CYP2E1, and CYP3A4/5 were higher in both in fibrosis and cirrhosis groups." (PMID 27203676, 2016). "Several previous studies reported that the activities of several CYPs, including CYP1A2, CYP2A6, CYP2D6, CYP2C19, CYP2E1, and CYP3A were decreased in cirrhosis patients relative to healthy subjects." (PMID 27203676, 2016). "In terms of Vmax, CYP2A6, CYP2B6, CYP2C9, CYP2D6, CYP2E1, and CYP3A4/5 were increased, while the Vmax values of CYP1A2 and CYP2C8 were decreased in both the cirrhosis and fibrosis groups compared to control subjects." (PMID 27203676, 2016). "CYP27A1, an oxidizer of cholesterol, and CYP2E1, a key enzyme in the microsomal ethanol oxidation system, were both up-regulated in most early (CTP class A) cirrhosis samples but significantly down-regulated by more severe, end-stage cirrhosis." (PMID 17121680, 2006).
alcohol (20 papers, 2012 to 2025). "Identify and characterize polymorphisms of genes ADH2, ADH3, ALDH2 and CYP2E1 in a Colombian population residing in the city of Bogotá and determine its possible relationship to the alcoholism." (PMID 26848198, 2015). "Since substance dependence requires interaction of multiple genes, the combination of genotypes ADH2*2, CYP2E1*1 combined with genotype homozygous ALDH2*1 found in this study could be leading to the population to a potential risk to alcoholism." (PMID 26848198, 2015). "In conclusion, we report that activated CB1 receptor induced ERRγ expression leads to hepatic FGF23 expression, which in turn up-regulates CYP2E1 expression and thereby exacerbates chronic alcohol-induced liver injury in mice." (PMID 38479224, 2024). "The total lignans of S. chinensis significantly reduced the protein and mRNA level of CYP2E1 in alcohol-induced liver injury rats." (PMID 37627597, 2023). "•In-depth analysis of TLR4/NF-κB p65 and CYP2E1/ROS/Nrf2 pathways expands insights, guiding precise therapies for alcohol-induced liver injury." (PMID 37868808, 2023). "For instance, cytochrome P450 2E1 (CYP2E1) is one of the major human hepatic CYP enzymes with direct relevance in alcoholism." (PMID 36982225, 2023). "Concurrently, its antioxidative prowess has a significant role in harmonizing the CYP2E1/ROS/Nrf2 pathway, thereby neutralizing the oxidative stress pivotal in alcohol-induced liver degeneration." (PMID 37868808, 2023). "Comparatively, the treatment of ethanol-administered rats with both doses of CGA (40 and 80 mg/kg) prevented response to alcohol intoxication, reducing the mRNA expression levels of Cyp2e1 and iNos, and increasing the level of Sod." (PMID 34836410, 2021). "These exosomal miRNAs and proteins such as CYP2E1 can be used the potential biomarkers for drug- or alcohol-induced liver injury." (PMID 30375433, 2018). "WGP provided a preventive potential against oxidative stress-related alcohol-induced liver damage through the inhibition of intracellular ROS accumulation and the down-regulation of CYP2E1 protein level." (PMID 27213339, 2016). "Apigenin (150–300 mg/kg/day p.o. for one month) has been shown to have a protective effect on alcohol-induced liver damage in alcoholic mice by modulating the expression of PPAR, which is involved in the synthesis of lipoproteins, and hepatic CYP2E1, which is associated with OS generation." (PMID 38629096, 2024). "However, during alcoholism, the expression of CYP2E1 increases, thereby generating a large number of ROS and causing severe liver damage." (PMID 36615880, 2023). "Hence, CYP2E1 is one of the candidate genes for alcohol dependence and plays an important role in rapidly reversing alcohol withdrawal and elevating alcohol concentrations after chronic consumption due to induction." (PMID 37259384, 2023). "Clomethiazole, a drug approved for alcohol withdrawal treatment (AWT) in some European countries, inhibits CYP2E1." (PMID 38851655, 2025). "Several genotyping studies have targeted alcohol dependence in Mexican Americans, focusing on the genes involved in alcohol metabolism (ADH, ALDH, and CYP2E1), and a subset of neurotransmitter-related genes (DRD2, 5-HTTLPR, and GABRβ3)." (PMID 25527893, 2014). "Notably, acetaminophen, which is prevalent in controlling high body temperatures caused by COVID-19, can also induce liver injury by activating hepatic cytochrome P450 2E1 (CYP2E1), which can occur in individuals with severe alcohol dependence." (PMID 39958382, 2023). "ADH2, ADH3, ALDH2, and CYP2E1 genotypes a population of 148 individuals with non-problematic alcohol and 65 individuals with alcoholism were determined with TaqMan probes and PCR-RFLP." (PMID 26848198, 2015).
injury (20 papers, 2016 to 2025). Damage inflicted on the body as the direct or indirect result of an external force, with or without disruption of structural continuity. "Polymorphisms associated with increased CYP2E1 activity in humans increase the incidence of drug-induced liver injury (DILI)." (PMID 32660103, 2020). "Collectedly, we suggested that SM had benefits in the treatment of APAP-induced acute liver injury in the early stage via CYP2E1 inhibition." (PMID 36557984, 2022). "Research results shows that overexpression of CYP2E1 can activate Nrf-2, which in turn plays a protective role in alcohol-induced liver injury." (PMID 34945529, 2021). "Cytochrome P450 2E1 (CYP2E1) plays an important role in both alcohol-induced and immune-mediated liver injury." (PMID 31881060, 2019). "In previous study, hepatoprotective effect of baicalin has been attributed to modulation of CYP2E1 activities in acetaminophen-mediated liver injury." (PMID 28951767, 2017). "Previous studies have shown that silymarin protects against various types of drug-induced liver injury, but whether the protective mechanism of silymarin against acetaminophen-induced liver injury is related to the CYP2E1 enzyme remains unclear." (PMID 36557984, 2022). "Furthermore, CHIP−/−-hepatocytes show little predisposition to MCD-WME-elicited or acetaminophen-induced liver injury, in spite of this marked hepatic CYP2E1-ROS-JNK1-activation." (PMID 27406999, 2016). "Moreover, ERRγ is a transcriptional mediator of the downstream effects of CB1R, where ERRγ blocks alcohol-induced cytochrome P450 2E1 (CYP2E1) expression, a major contributor to alcohol-induced reactive oxygen species (ROS) and liver injury, to ameliorate chronic alcohol-induced liver injury." (PMID 31035653, 2019). "CYP2E1 is responsible for the transformation of NAPQI, and its expression is correlated with the extent of APAP-induced liver injury." (PMID 39962071, 2025). "It has been reported that the upregulated expression of CYP2E1 and activation of the NF-κB pathway are involved in the pathogenesis of ETH-induced liver injury." (PMID 35685625, 2022). "APAP toxicity is dependent on the expression of Cyp2e1; therefore, it is not surprising that APAP-induced lung injury consistently occurs at hepatotoxic APAP exposures in rodents." (PMID 41153729, 2025).
lung carcinoma (19 papers, 2011 to 2024). "CYP2E1 has been associated with altered susceptibility with increased risk of development of other malignant tumors such as lung cancer." (PMID 37796968, 2023). "Recently, it was shown that CYP2E1 was associated with liver cancer, lung cancer, and ovarian cancer by metabolizing and activating procarcinogens and inducing inflammation." (PMID 37283464, 2023). "CYP2E1 Rsa Ι/Pst Ι polymorphism and lung cancer susceptibility: a meta‐analysis involving 10,947 subjects." (PMID 29924497, 2018). "Over the last two decades, several studies have explored the association of the CYP2E1 polymorphism with the risk of lung cancer, gastric cancer, and pancreatic cancer." (PMID 24151610, 2013). "Recently, several global meta-analyses have summarized the individual findings on PTGS2 and CYP2E1 genes and confirmed the significantly protective effect of rs5275, rs2031920 and rs6413432 mutant alleles on lung cancer." (PMID 22761909, 2012). "To expand the findings, we reported a potential synergism between PTGS2 and CYP2E1 genes on lung cancer risk, as reflected by haplotype and interaction analyses." (PMID 22761909, 2012). "Due to these important functions, PTGS2 and CYP2E1 genes were investigated as logical candidates for lung cancer susceptibility." (PMID 22761909, 2012). "The aim of this study was to investigate the association of five extensively-studied polymorphisms in PTGS2 (rs689466, rs5275, rs20417) and CYP2E1 (rs2031920, rs6413432) genes with lung cancer risk in a large northeastern Chinese population." (PMID 22761909, 2012). "Our findings demonstrated a potentially synergistic association of PTGS2 and CYP2E1 polymorphisms with the underlying cause of lung cancer in northeastern Chinese." (PMID 22761909, 2012). "Many studies have evaluated the association of polymorphisms in PTGS2 and CYP2E1 genes with lung cancer; however, the results have been inconsistent, and the biological effects based on statistical reasoning are still elusive." (PMID 22761909, 2012). "Together, these results demonstrate that CYP2E1 plays a critical role in lung cancer, and it may be a potential target associated with inflammation in lung cancer." (PMID 37875398, 2023). "Of note, we found greater levels of inflammatory factors such as IL‐4, IL‐10 and TGF‐β were associated with a higher CYP2E1 level in peritumoral tissues, indicating that CYP2E1 may be related to the inflammation response in lung cancer." (PMID 37875398, 2023). "In this study prostaglandin-endoperoxide synthase 2 (PTGS2) and cytochrome P450, family 2, subfamily E, polypeptide 1 (CYP2E1) were selected as candidate genes susceptible to lung cancer based on their critical involvement in the mechanism of lung carcinogenesis." (PMID 22761909, 2012). "Moreover, genotyping data from the PTGS2 and CYP2E1 genes, incorporating the haplotype and synergism analytical strategy would facilitate the identification of individuals at high risk of developing lung cancer in future clinical screening." (PMID 22761909, 2012). "Moreover, alcohol may increase the uptake of environmental carcinogens from tobacco smoke by inducing activation of CYP2E1 or through damaged cell membranes by direct effect of alcohol to enhance the risk of lung cancer." (PMID 22815780, 2012). "The novel CYP2E1 inhibitor Q11, namely 1-(4-methyl-5-thiazolyl) ethenone, is effective in treating lung cancer in mouse models." (PMID 39418180, 2024). "To gain insight into how the expression of CYP2E1 was altered in lung cancer, we quantified the level of CYP2E1 in the peritumoral tissues of non‐small cell lung cancer (NSCLC) patients." (PMID 37875398, 2023). "The novel developed CYP2E1 inhibitor Q11, 1‐(4‐methyl‐5‐thialzolyl) ethenone, is effective on lung cancer in mice via regulation of the macrophage polarization in the tumor inflammatory microenvironment." (PMID 37875398, 2023).
lung carcinoma (continued). "It is discovered and validated CYP2E1 as a novel inflammatory target in lung cancer by patients and Cyp2e1‐/‐ mice." (PMID 37875398, 2023). "We demonstrate that a novel CYP2E1 inhibitor, Q11, is effective on lung cancer via regulation of the inflammatory microenvironment." (PMID 37875398, 2023). "The novel CYP2E1 inhibitor Q11, 1‐(4‐methyl‐5‐thialzolyl) ethenone, is effective in the treatment of lung cancer in mice, which can inhibit cancer cells by changing macrophage polarization rather than directly act on the cancer cells." (PMID 37875398, 2023). "To determine if CYP2E1 is a therapeutic target for lung cancer, we established the Lewis lung orthotopic xenograft model using Cyp2e1 knockout (Cyp2e1−/−) mice, and H&E staining was performed to identify the tumor." (PMID 37875398, 2023). "Our study provides new insight into the crucial role of CYP2E1 in lung cancer and demonstrates that CYP2E1 can be an inflammatory target in lung cancer." (PMID 37875398, 2023). "In our study, CYP2E1 was identified as a novel inflammatory target in lung cancer, which provides the possibility to develop new drugs for lung cancer." (PMID 37875398, 2023). "Here, it is found that CYP2E1 is significantly higher in the peritumoral tissue of non‐small cell lung cancer (NSCLC) patients and lung tumor growth is significantly impeded in Cyp2e1−/− mice." (PMID 37875398, 2023). "Previous studies reported that CYP2E1, which is involved in the bioactivation of urethane, decreased urethane metabolism in vivo and was relatively resistant to urethane‐induced lung cancers." (PMID 34612013, 2021). "The relationship between CYP2E1 and NOC metabolism is so profound that it has been reported that depletion of CYP2E1 confers resistance to smoking-induced lung cancer." (PMID 31694233, 2019). "The primary alcohol metabolism cytochrome P450 is CYP2E1; CYP2E1 is also essential in the metabolism of the anti-cancer drugs cisplatin and etoposide, which are frequently used in lung cancer chemotherapy." (PMID 28187735, 2017). "This study provides supporting evidence for further investigation on pathophysiological mechanisms of PTGS2 and CYP2E1 genes in lung cancer." (PMID 22761909, 2012). "The data demonstrate that CYP2E1 may be a novel inflammatory target and that Q11 is effective on lung cancer by regulation of the inflammatory microenvironment." (PMID 37875398, 2023). "Given the potential effects of CYP2E1 on lung cancer, we evaluated whether Q11 is effective on lung cancer." (PMID 37875398, 2023). "Although studies have shown that CYP2E1 can participate in the occurrence and development of lung cancer and other lung diseases, the mechanism by which CYP2E1 affects lung cancer is unknown." (PMID 37875398, 2023). "In summary, our study supports CYP2E1 as a new target in lung cancer." (PMID 37875398, 2023). "In this study we found significant associations of PTGS2 and CYP2E1 polymorphisms with the susceptibility to lung cancer in northeastern Chinese." (PMID 22761909, 2012). "Thus, our data reveal that CYP2E1 may be a potential target for prevention and treatment of lung cancer." (PMID 37875398, 2023). "Absence of association between CYP2E1*5B polymorphism and lung cancer among patients from Rio de Janeiro has been previously observed; this could be explained by the fact that alcohol is not a lung carcinogen." (PMID 24151610, 2013). "The three studied CYP2E1 SNPs are in the intronic region of the gene and there is no clear information about their functionality but the wild-type allele of rs6413432 has been shown to be associated with an increased risk of prostate cancer and other cancers such as lung cancer." (PMID 29445914, 2019).